MACC1 (MET transcriptional regulator MACC1)
Diseases named in the same sentence as MACC1 in open-access papers (continued):
Sharing a sentence is not in itself a finding about the gene and the disease.
cancer (continued). "MACC1 was newly identified as an oncogene that controls hepatocyte growth factor/Met pathway and promotes cancer cell migration and invasion in both cell cultures and xenograft models." (PMID 30515418, 2018). "It has been demonstrated that MACC1 should be defined as a prognostic and metastatic biomarker for various cancers." (PMID 30021598, 2018). "Cancer-specific activation of MACC1 expression is possibly mediated by aberrantly activated cell signaling pathways in cancer cells." (PMID 30082743, 2018). "Many studies have demonstrated that MACC1 overexpression is correlated with worse clinical outcomes in cancer patients." (PMID 30515418, 2018). "This is—to the best of our knowledge—the first identification of inhibitors restricting cancer progression and metastasis via the novel target MACC1." (PMID 28570591, 2017). "Many further studies reported that MACC1 can act as a decisive driver for the transition from adenoma to carcinoma and thus initiates cancer progression and ultimately metastasis." (PMID 28570591, 2017). "MACC1, a key regulator of cell growth and invasion in cancer development, was identified as a down-stream target of miR-497." (PMID 27911852, 2017). "This HTS revealed mevastatin and rottlerin as the most promising hits for MACC1 transcriptional inhibition, providing the chance to reposition these drugs in cancer therapy." (PMID 28570591, 2017). "Taken together, our study uncovers the first small-molecule inhibitors of MACC1-induced cancer progression and metastasis formation in vitro and in vivo, thereby suggesting their strong therapeutic relevance." (PMID 28570591, 2017). "This suggests that downregulation of miR-218 and MACC1 upregulation are early events during cancer development even before metastasis." (PMID 27462788, 2016). "MACC1-positive staining was mainly confined in the cytoplasm of cancer cells, and KAI1-positive staining was mainly confined in the membrane and cytoplasm of cancer cells." (PMID 27793161, 2016). "Meanwhile, MACC1 contributes to tumorigenesis through the promotion of cancer cell proliferation and invasion through activation of the HGF/ Met signaling pathway." (PMID 27832750, 2016). "These cumulative evidences suggest that miR-218-induced effects on migration, invasion and colony formation in different cancer entities are at least in part a result of the inhibition of the MACC1 expression." (PMID 27462788, 2016). "From the literature and gene expression depository databases, like The Cancer Genome Atlas (TCGA) and Gene Expression Omnibus (GEO), we know that miR-218 is downregulated and, simultaneously, MACC1 is upregulated in different cancer entities." (PMID 27462788, 2016). "In this study, we detected the association between MACC1 and KAI1 expression in patient cancer tissues as well as compared their expression with clinicopathology, metastasis, and prognosis of GAC." (PMID 27793161, 2016). "Including our previous studies on MACC1 and other MACC1 and miR-218 published studies demonstrated that high MACC1 and low miR-218 expressing cancer cells are resistant to chemotherapy." (PMID 27462788, 2016). "While most of the published data on MACC1 expression was done in cancer specimens, our study here in precancerous lesions highlights important roles of MACC1 at earlier stages." (PMID 27439755, 2016). "This very important finding highlights that MACC1 blood levels can be used to distinguish patients with neoplastic transformation before reaching the carcinoma state." (PMID 27439755, 2016). "In the end, since there was extreme heterogeneity among the 15 studies selected for pooled OS, a metaregression analysis was performed to recognize the source of heterogeneity by publication year, cancer subtypes, and MACC1 measurement in the OS dataset." (PMID 26090393, 2015).
cancer (continued). "Numerous studies have previously shown that MACC1 is abnormally expressed in various human malignances, and that it acts as a metastatic pacemaker in colorectal, gastric and various other cancer cells." (PMID 26043756, 2015). "Positive MACC1 signals were detected in 66 of the 73 RPC cancer lesion samples (∼90.4%), as well as in 24 of the 32 ANRPET (∼75.0%) and 29 of the 41 NRPET (∼70.7%) samples we examined in this study." (PMID 24949951, 2014). "Elevated MACC1 expression has thus been suggested to serve as an independent prognostic indicator for cancer recurrence, potential exacerbation from benign into malignant tumors, or under certain circumstances, the onset of metastasis." (PMID 24949951, 2014). "The role of MACC1 as a biomarker for cancer progression and survival was meanwhile also reported for other solid cancers, such as gastric, lung, hepatocellular and ovarian cancer." (PMID 23166620, 2012). "MACC1 levels in the primary tumors were found to be significantly higher in cancers that metachronously developed distant metastases compared to those which did not metastasize within a 12-year follow-up." (PMID 23166620, 2012). "This blood-based assay for circulating MACC1 transcripts, which can be quantitated on a routine basis, is clinically applicable for diagnosis, prognosis, and therapeutic monitoring of cancer patients." (PMID 23166620, 2012). "This assay for circulating MACC1 transcripts, which can be quantitated on a routine basis, is clinically applicable for diagnosis, prognosis, and therapeutic monitoring of cancer patients." (PMID 23166620, 2012). "The role of MACC1 in cancer progression and metastasis makes it a promising therapeutic target." (PMID 40354443, 2025). "MACC1 and CCN1 are both implicated in cancer metastasis, adhesion, and survival." (PMID 38396744, 2024). "In general, MACC1 has already been described in the stemness context in different cancer entities." (PMID 38339354, 2024). "Therefore, functionally, MACC1 is involved in mediating cellular proliferation, metabolic activity, cancer cell stemness properties, and angiogenesis, which all lead to the promotion of a metastasis-associated phenotype." (PMID 38611008, 2024). "When we observed the transition to malignant carcinomas in vil-MACC1/APCmin mice, we found by transcriptomics of vil-MACC1/APCmin vs. APCmin mice a tremendous expression of stemness genes, such as Nanog (direct induction) and Oct4 (indirect induction), by MACC1." (PMID 38339354, 2024). "Metastasis-Associated in Colon Cancer 1 (MACC1), a newly identified oncogene and regulator of the HGF/Met signaling pathway, has been shown to play a critical role in the development and progression of several types of cancer." (PMID 38021160, 2023). "Research suggests that the MACC1 protein may be caused by genetic variation, which restricts c-MET expression, hence encouraging the spread of cancer cells." (PMID 36979146, 2023). "This is interesting as MACC1 has already been reported to promote angiogenesis in many cancers." (PMID 37841442, 2023). "Our results clearly indicate that cantharidin and, to a lesser extent, its analogue norcantharidin are promising compounds for efficient anti-metastatic therapy targeting the metastasis-inducing genes S100A4 and MACC1 for personalized medicine for cancer patients." (PMID 36674695, 2023). "MACC1 is involved in promoting epithelial mesenchymal transformation, in cancer metastasis, in blood vessels and lymphatic vessels, and in enhancing the Warburg effect and cancer immunotherapy." (PMID 36979146, 2023). "Despite the known association of MACC1 SNPs with various cancers, their role in patients with UCC has not been established." (PMID 38021160, 2023). "Macc1 is known to regulate a number of cellular functions in cancer including cell proliferation." (PMID 37841442, 2023). "Pan-cancer analysis showed that MACC1 mRNA was upregulated in COAD." (PMID 36545127, 2022).
cancer (continued). "A positive correlation between FN1 and MACC1 was also observed in ten cancer types in TCGA." (PMID 36333284, 2022). "It has been found that MACC1 has an increasing influence on many cancers." (PMID 35874635, 2022). "Therefore, among other natural products, we investigated the MACC1-dependent effect of curcumin, which is accounted as one of the most promising natural compounds to restrict cancer progression." (PMID 36432477, 2022). "Thus, the current study investigated MACC1-induced elevated cancer cell motility, focusing on the biomechanics and migration of CRC cells on the single and multicellular level." (PMID 35740524, 2022). "The context of MACC1 dysregulation in cancers is, however, still poorly understood." (PMID 35406521, 2022). "Subsequently, MACC1 was knock-down in cancer cell lines, C-33A and Caski." (PMID 34939526, 2022). "High MACC1 expression, CIN, DNA copy number gains, and CMSs, potentially define the molecular risk for cancer metastasis and might serve for refined diagnostic and patient tailored treatment decisions." (PMID 35406521, 2022). "miR-944 inhibits EMT progression in cancer cells by targeting two genes (MACC1 and GATA6)." (PMID 36077769, 2022). "MACC1 is a known driver for cancer metastasis and a prominent modulator of drug response in CRC." (PMID 35884519, 2022). "Firstly, we measured and analyzed the expression of MACC1 in CC tissues and para-carcinoma tissues." (PMID 34939526, 2022). "Although MACC1 is associated with EMT in other cancers, their relationship in NPC has not been characterized." (PMID 33854976, 2021). "In addition to the role of MACC1 in cancer metastasis and progression, MACC1 was suggested to have a crucial role in the TME and the immune escape mechanisms." (PMID 34577857, 2021). "We found that MACC1 permits numerous effects on cancer metabolism." (PMID 33652667, 2021). "Although the MACC1-induced proliferation of CRC cells can now be linked to enhanced TfR and EGFR recycling, more cancer-related RTKs and respective downstream signaling pathways may be affected by this mechanism and should be the focus of future studies." (PMID 33469705, 2021). "In brief, MACC1 could be identified as a candidate prognostic biomarker and play a regulatory role as TF among the eight cancer types." (PMID 33751856, 2021). "These investigations implicate MACC1 as a multifunctional regulator of cancer progression." (PMID 34221989, 2021). "Consistent with a previous study on uterine cervical cancer, the correlation between MACC1 and the EMT-related proteins, vimentin and E-cadherin, observed in this study indicate the association between MACC1 and EMT in NPC, thus adding NPC to the list of cancers previously reported to involve EMT." (PMID 33854976, 2021). "In summary, we demonstrate that MACC1 is an important regulator of metabolism in cancer cells." (PMID 33652667, 2021). "We investigated the inhibitory impact of saffron on MACC1-induced cancer cell growth and motility." (PMID 32756469, 2020). "As previous studies have suggested that the possible effects of MACC1 on cancer cell proliferation are mediated via the HGF/c-Met signaling pathway, we explored whether the MACC1-induced effects on OS were mediated via the HGF/c-Met pathway." (PMID 33425885, 2020). "However, the exact role of MACC1 SNPs and haplotype in various cancers including HCC remained controversial and incompletely." (PMID 32047570, 2020). "With this study, we want to explore the possibility of restoring the susceptibility of multi-drug resistant CRC cells to common, but efficient anti-cancer drugs like doxorubicin, by combination therapy and repositioning of drugs that target the expression of MACC1." (PMID 32391276, 2020). "Importantly, MACC1 is also indicated to be a transcriptional regulator of c-Met which is receptor tyrosine kinase aberrantly activated in human cancers." (PMID 33425885, 2020).
cancer (continued). "Although these observations implicate MACC1 as a critical regulator of cancer progression, whether MACC1 also has a potential role in the development and progression of OS remains unclear." (PMID 33425885, 2020). "However, more investigation is needed to solidify the significance of the prognostic stratification of MACC1 expression in cancers." (PMID 30805302, 2019). "Moreover, higher circulating MACC1 transcripts and soluble MACC1 proteins have also been found relating to unfavorable prognosis for cancer patients." (PMID 30805302, 2019). "Therefore, more studies are necessary to explore and evaluate the clinical significance of the circulating MACC1 protein among different types of cancers." (PMID 30370603, 2019). "Thereafter, a wealth of studies have been carried out in variety of malignancies, strengthening the potential application of both MACC1 transcripts and protein expression as a novel prognostic indicator, and MACC1 as a therapeutic target was recommended for cancers." (PMID 30805302, 2019). "MACC1 has been shown to affect recurrence, metastasis, and prognosis in various cancers." (PMID 28253891, 2017). "We also established the detection of circulating MACC1 transcripts in cancer patient blood." (PMID 27439755, 2016). "Now, more and more studies have demonstrated that MACC1 could also be a metastatic and prognostic factor for various human cancers, including pancreatic, liver, lung, ovary, breast, gastric, malignant glioma, and cervical carcinoma." (PMID 27793161, 2016). "Together with MACC1-regulating cancer growth via the activation of the HGF/c-MET/PI3K/AKT signaling pathway, we purposed that MACC1 might induce trastuzumab resistance by regulating the Warburg effect via the PI3K/AKT signaling pathway." (PMID 27581375, 2016). "However, in dealing with MACC1 APA sites a broader screening is required between different cancer cell lines and entities for better understanding of this phenomenon." (PMID 27462788, 2016). "Therefore, MACC1 is one of the key regulators of hallmarks of cancer like cell proliferation, apoptosis, metastatic events (migration, invasion, epithelial mesenchymal translation (EMT)) and angiogenesis, as well as its role in cancer cell metabolism." (PMID 27462788, 2016). "Due to this reason and the important role of MACC1 upregulation in different cancer entities, we have investigated whether MACC1-3′-UTR contains any APA sites." (PMID 27462788, 2016). "Decreased or lost expression of KAI1 might lose inhibiting the activation of MACC1, angiogenesis and lymphangiogenesis, and stabilization of E-cadherin-β-catenin complexes to promote cancer cell invasion and metastasis." (PMID 27793161, 2016). "At the same time, abnormal expression of MACC1 could further promote cancer cell invasion and metastasis." (PMID 27793161, 2016). "Since, it is known that MACC1 is upregulated in different cancer entities." (PMID 27462788, 2016). "Along with Robo1, other molecules like receptor protein tyrosine phosphatase alpha (RPTPα), myocyte enhancer factor 2D (MEF2D), and runt-related transcription factor 2 (RUNX2) are post-transcriptional target molecules of miR-218, which are known to induce cancer metastasis like MACC1." (PMID 27462788, 2016). "Although MACC1 has been demonstrated to play important role in GC, it is completely unknown whether it plays any role in VM process of cancers." (PMID 25895023, 2015). "In addition, MACC1 has also emerged as a predictive indicator for recurrence-free survival, and overall survival (OS) of cancer patients in several quantitative studies performed in various solid tumors." (PMID 24949951, 2014). "The genes MACC1, PEG10, CALCOCO1, and MEF2C have been found to be implicated in cancer." (PMID 24086395, 2013).
cancer (continued). "Since MACC1 represents a promising target for anti-metastatic therapies, circulating MACC1 transcripts may prove to be an ideal read-out for monitoring therapeutic response of future interventions targeting MACC1-induced metastasis in cancer patients." (PMID 23166620, 2012). "We detected MACC1 transcripts in plasma of all cancer patients." (PMID 23166620, 2012). "While all of these highlight the importance and potential that MACC1 possesses as a biomarker for metastasis, additional research is needed to fully elucidate MACC1’s specific physiological functions as well as further understand its role in mediating key cancer processes." (PMID 38611008, 2024). "Consequently, further research into MACC1-specific drugs may be an additional route to inhibit cancer cell migration." (PMID 37051546, 2023). "Thus, GIPC1-targeting intervention strategies might interdict the MACC1-induced cancer metastasis formation." (PMID 38144523, 2023). "Since the discovery of MACC1, its unique structure, imbedding different protein interaction sites such as a SH3 domain, transcriptional activation, post-translational modifications, and its role in promoting nearly all cancer hallmark capabilities have been elucidated." (PMID 36674695, 2023). "SNPs may change MACC1 expression or function, thus affecting the prognosis of cancer." (PMID 36979146, 2023). "MACC1 is directly associated with the regulation of c-MET expression, subsequently inducing EMT via elevated HGF/c-MET signalling, but also of the pluripotency marker NANOG and the cell adhesion factor SPON2, both contributing to cancer progression and metastasis." (PMID 35597866, 2022). "Besides, MACC1/SPINT1 panel was established to effectively predict survival in eight cancers." (PMID 33751856, 2021). "Therefore, MACC1 is an important regulator of cancer metabolism." (PMID 33652667, 2021). "More importantly, MACC1 status could further improve the prognostic power for stratified clinical parameters, such as basic patient characteristics (patient age and gender) or distinct pathological factors (cancer subtype, TNM status and AJCC stages)." (PMID 30805302, 2019). "The results demonstrated that reactivated miR-25-3p by the mimics abrogated the MACC1-mediated elevation of KLF4 at the mRNA and protein levels in two cancer cell lines." (PMID 39695175, 2024). "Taken together, RNA sequencing performed on PDO and PDX models demonstrated increased MACC1 expression in ALDH1-positive CSCs, highlighting its involvement in cancer stemness." (PMID 38339354, 2024). "Since MACC1 is decisive for metastasis induction, the importance of the stemness gene LGR5 in cancer metastasis is crucial to extract." (PMID 38339354, 2024). "MACC1 regulates the expression of Oct4, Stat3, AKT, and ClclinD1 by regulating the transcription of Nanog, thereby promoting cancer metastasis." (PMID 36979146, 2023). "Since silencing GIPC1 is already an acknowledged tool in cancer research, and GIPC1 was found in the nuclei, we tested for a possible action of GIPC1 on the regulation of MACC1 gene expression." (PMID 38144523, 2023). "Other authors describe NEK2, MACC1, REG1A, KIF18A, RET, and TIP60 as possible PM-related cancer genes." (PMID 37629011, 2023). "MACC1 is involved in many aspects of cancer progression including promotion of epithelial-to-mesenchymal transition (EMT), acceleration of cancer metastasis and induction of cell proliferation." (PMID 37664587, 2023). "Taken together, these findings suggest that ZFAS1 plays a carcinogenic role in various human cancers and that the ZFAS1/hsa-miR-642a-5p/MACC1 axis constitutes the potential regulatory pathway that promotes the progression of COAD." (PMID 36545127, 2022). "In particular, PER2 KO cells showed the highest increase in cell invasion, possibly also due to a significant increase in MACC1 and a decrease in ECAD expression, leading to a more aggressive cancer phenotype by activating EMT markers." (PMID 35884519, 2022).